EGFR (epidermal growth factor receptor)
Diseases named in the same sentence as EGFR in open-access papers (continued):
Sharing a sentence is not in itself a finding about the gene and the disease.
lung squamous cell carcinoma (177 papers, 1996 to 2026). "We herein report a rare EGFR‐mutated squamous cell lung carcinoma that responded to osimertinib, a third‐generation EGFR‐TKI." (PMID 40620186, 2025). "EGFR‐tyrosine kinase inhibitors are generally less effective for EGFR‐mutated squamous cell lung carcinoma." (PMID 40620186, 2025). "In contrast, another study reported a lower response rate in EGFR‐mutated squamous cell lung carcinoma and shorter PFS." (PMID 40620186, 2025). "We herein present a case of EGFR‐mutated squamous cell lung carcinoma that responded to osimertinib." (PMID 40620186, 2025). "The reported rate of EGFR mutations in patients with squamous cell carcinoma of the lung is 4.2%–7%." (PMID 40620186, 2025). "We herein presented a rare EGFR‐mutated squamous cell lung carcinoma that responded well to osimertinib." (PMID 40620186, 2025). "Microtubules and their post-translational modifications have been implicated in EGFR transport and chemotherapy resistance in lung squamous cell carcinoma." (PMID 41381443, 2025). "1.A patient diagnosed with lung squamous cell carcinoma exhibiting rare concurrent epidermal growth factor receptor mutation (G719C and S768I) showed favorable response to afatinib, achieving 10 months of progression-free survival." (PMID 39166093, 2024). "Tumor heterogeneity, especially in the metastatic phase, is influenced by various factors including histological subtypes (such as adenocarcinoma and squamous cell lung cancer) and genetic mutations (such as those in EGFR, BRAF, KRAS, and ALK translocations)." (PMID 39518079, 2024). "This is partially explained by the higher proportion of adenocarcinoma and EGFR-driver mutations in Asia and squamous cell lung cancer in Europe." (PMID 37444585, 2023). "The overall frequency of the EGFR exon 19 deletion mutation found in adenocarcinomas was 84.4% (38 of 45), followed by 13.3% (6 of 45) of large cell lung cancer and 2.2% (1 of 45) of squamous cell lung cancer." (PMID 38008767, 2023). "In squamous cell lung cancer, patients with the EGFR Q787Q polymorphism have been reported to have poorer outcomes for stage I and II disease." (PMID 35387120, 2022). "Compared with advanced lung adenocarcinoma patients, the EGFR mutation rate of patients with lung squamous cell carcinoma (SCC) is much lower, about 4.2%-23.8% only." (PMID 33869057, 2021). "Especially, Recent processes in molecular biology have confirmed that FGFR1 amplification is detected in approximately 20% of lung squamous cell carcinoma (SqCC) 19 and is associated with the mechanism of acquired resistance to EGFR-TKIs 26,27." (PMID 32626515, 2020). "Squamous cell lung cancers (SCLCs) with both EGFR mutation and high expression of PD-L1 are very rare." (PMID 32291904, 2020). "The role of the epidermal growth factor receptor (EGFR) mutation status testing in lung squamous cell carcinoma (SqCC) remains controversial." (PMID 32667739, 2020). "In 96 lung squamous cell carcinoma blood samples, there were 8 (8.3%) EGFR mutations, 7 (7.3%) KRAS mutations, 6 (6.3%) PIK3CA mutations and 1 (1.0%) BRAF mutations." (PMID 31749831, 2019). "In 134 lung squamous cell carcinoma tissue samples, there were 7 (5.2%) EGFR mutations, 6 (4.5%) KRAS mutations, 12 (9.0%) PIK3CA mutations, 1 (0.7%) BRAF mutations and 1 (0.7%) MET amplifications." (PMID 31749831, 2019). "The combined objective response rate, disease control rate and median progression-free survival were 31.6% (95%CI, 24.1%∼40.2%), 72.0% (95% CI, 63.5%∼79.2%) and 3.08 months (95% CI, 2.31-3.84 months) in lung squamous cell carcinoma patients with EGFR mutation." (PMID 28881841, 2017). "This pooled analysis aims to evaluate the efficacy of epidermal growth factor receptor (EGFR)-tyrosine kinase inhibitors (TKIs) in lung squamous cell carcinoma with EGFR mutation." (PMID 28881841, 2017).
lung squamous cell carcinoma (continued). "The results of our prospective multicenter study (IGNITE study) demonstrated that in an Asian population with lung squamous cell carcinoma, the EGFR mutation frequency was 10%26." (PMID 27811976, 2016). "growth factor receptor (EGFR) is commonly overexpressed in lung squamous cell carcinoma and has been associated with impaired prognosis." (PMID 27760595, 2016). "The EGFR mutation rate detected in our study is consistent with that of adenocarcinoma and considerably higher than that of squamous cell carcinoma of the lung." (PMID 26923333, 2016). "A total of 139 patients undergoing treatment for na?ve lung squamous cell carcinomas with tumor tissue samples available for testing were recruited.EGFR and KRAS mutation statuses of the tumor samples were detected using a mutant enriched liquid chip." (PMID 26483334, 2015). "Case 2 was a 73-year-old Japanese male diagnosed with stage IV squamous cell lung carcinoma and bone metastasis who had the EGFR mutation, L747S." (PMID 24396447, 2014). "EGFR expression is associated with smoking history and is significantly upregulated in lung squamous cell carcinoma." (PMID 22322523, 2012). "Clinical cases of EGFR‐mutated squamous cell lung carcinoma treated with first‐line Osimertinib." (PMID 40620186, 2025). "The reported rate of EGFR mutations in patients with squamous cell lung carcinoma is 4.2%–7%." (PMID 40620186, 2025). "Squamous cell lung carcinomas are associated with many genomic abnormalities, and EGFR mutations alone may be less common." (PMID 40620186, 2025). "Although EGFR variants are relatively rare in lung squamous cell carcinomas, they do occur and this may further limit the generalizability of the present results." (PMID 40299437, 2025). "Osimertinib may be an option for the treatment of patients with EGFR‐mutated squamous cell lung carcinoma." (PMID 40620186, 2025). "It currently remains unclear why EGFR‐TKIs are less effective for EGFR‐mutated squamous cell lung carcinomas than for adenocarcinomas." (PMID 40620186, 2025). "Epidermal growth factor receptor (EGFR) mutations in squamous cell lung carcinoma are rare." (PMID 40620186, 2025). "We encountered a rare EGFR‐mutated squamous cell lung carcinoma that responded well to osimertinib." (PMID 40620186, 2025). "However, in actual clinical practice, we encountered a certain percentage of EGFR mutations in lung squamous cell carcinoma (LUSC)." (PMID 40969259, 2025). "Therefore, in EGFR‐mutated squamous cell lung cancer, we need to consider treatments that are potentially beneficial and have few adverse events, such as TKIs." (PMID 40620186, 2025). "Other causes of resistance to EGFR TKIs include amplification of MET gene (approximately 20% of patients), small cell or squamous cell lung cancer transformation, loss of the primary EGFR gene mutation, secondary mutations in KRAS or PIK3CA genes, and the occurrence of disorders in ALK gene." (PMID 35522668, 2022). "The prevalence of EGFR mutation in lung sarcomatoid carcinoma is lower than that reported in our patients with adenocarcinoma but similar to that reported in our patients with squamous cell lung cancer." (PMID 36200011, 2022). "The patient admitted to our hospital was 58 years old, female, with a rare case of stage IB lung squamous cell carcinoma (LUSC) harboring both epidermal growth factor receptor (EGFR) p.L858R mutations and high expression of programmed death ligand-1 (PD-L1) (tumor proportion score (TPS)=80%)." (PMID 36338754, 2022). "The frequency of EGFR mutations has been reported to be 47.9% in adenocarcinoma and 4.6% in lung squamous cell carcinoma among East Asian populations, and 19.2% in lung adenocarcinoma and 3.3% in lung squamous cell carcinoma among Western populations." (PMID 34548567, 2021). "The EGFR-TKIs had a modest response for EGFR mutated lung squamous cell carcinoma patients and might be a selective option for those patients." (PMID 28881841, 2017).
lung squamous cell carcinoma (continued). "In addition to BMP7, a separate study also found that activation of the BMP2/4-BMPR signaling pathway conferred resistance to epidermal growth factor receptor tyrosine kinase inhibitors (EGFR-TKIs) in patients with lung squamous cell carcinoma harboring mutations in the EGFR gene." (PMID 36353620, 2022). "The NCCN recommends that all patients, except those with squamous cell lung cancer who have a smoking history, should be screened for the presence of activating EGFR mutations, i.e., deletions in exon 19 or point mutation L858R in exon 21, to identify those who will benefit from EGFR TKI treatment." (PMID 30891428, 2019). "For instance, suppression of EGFR can stimulate PARP‐mediated DNA repair in EGFR‐mutant squamous cell lung cancer, leading to increased tumor cell survival." (PMID 41362117, 2025). "The majority of patients (60.7%) had squamous cell lung cancer, 44.3% had stage IIIc, and 14.3% had EGFR-positive NSCLC." (PMID 40299530, 2025). "Epidermal growth factor receptor (EGFR) mutation is the most frequently found oncogene driver mutation in non-small cell lung cancer (NSCLC), but its prevalence in lung squamous cell carcinoma (LSCC) is rare." (PMID 40351934, 2025). "A monoclonal antibody, necitumumab, specifically approved for squamous cell lung cancer, similarly inhibits EGFR activation." (PMID 39063109, 2024). "In the present study, the tumors in cases NCCLu-237 and NCCLu-253 consisted of an ALK-positive large-cell neuroendocrine carcinoma and an EGFR-mutant squamous cell lung carcinoma, respectively." (PMID 38398169, 2024). "Such promising prognostic and predictive markers are missing in squamous cell carcinoma of the lung (LSCC), with the exception of PD-L1 and rare mutations in Epidermal Growth Factor Receptor (EGFR) and rearrangements in Anaplastic Lymphoma Kinase (ALK)." (PMID 37445817, 2023). "Another group found that BMP2/4-BMPR-SMAD1/570S6K activation promoted resistance to erlotinib, an EGFR-TKI, in lung squamous cell carcinomas with EGFR mutations." (PMID 36353620, 2022). "Although the mutation rate of EGFR, ALK, and ROS genes in lung squamous cell carcinoma is low, less than 10%, there are still a few patients with mutant targets who can benefit from targeted drugs." (PMID 36411824, 2022). "Given the rarity of actionable driver genes in squamous cell lung cancer (SQCC), the frequency of SQCC patients simultaneously carrying EGFR driver gene mutation and having PD-L1 over-expression is extremely low." (PMID 35984168, 2022). "Although afatinib is the standard drug for the treatment of lung squamous cell carcinoma (SCC) with EGFR overexpression, attempts have been made to use this irreversible blocker for other EGFR expressing tumors." (PMID 34596822, 2022). "Currently, EGFR amplification is being used as an inclusion criterion in three clinical trials for squamous cell lung carcinoma with EGFR tyrosine kinase inhibitors (TKIs)." (PMID 35565304, 2022). "EGFR-inhibitors include EGFR-TKIs, a standard therapy for EGFR-mutated NSCLC, and anti-EGFR antibodies, a standard therapy for CRC, HNSCC, and squamous cell lung cancer." (PMID 33801379, 2021). "The therapeutic efficacy of epidermal growth factor receptor tyrosine kinase inhibitors (EGFR-TKIs) in advanced EGFR-mutant lung squamous cell carcinoma (SCC) patients remains uncertain." (PMID 34195081, 2021). "In this regard, EGFR, one of the ERBB family tyrosine kinases, is amplified and highly overexpressed in HNSCC and lung squamous cell carcinoma, and mutated and activated in many cancer types including lung adenocarcinoma and glioblastoma." (PMID 34725466, 2021). "The FDA has approved afatinib as a first-line treatment for metastatic NSCLC EGFR-mutant cancers, as well as for advanced squamous cell carcinoma of the lung following failure of platinum-based chemotherapy." (PMID 30975211, 2019).
lung squamous cell carcinoma (continued). "Afatinib has been approved as first-line treatment for patients with EGFR mutation-positive NSCLC and second-line treatment for patients with squamous cell carcinoma of the lung." (PMID 29433585, 2018). "Here, we describe an Asian lung squamous cell carcinoma patient demonstrating frank disease progression following chemotherapy and EGFR inhibitor treatment." (PMID 28123873, 2016). "EML4-ALK fusion occurred more frequently than EGFR and KRAS mutations in patients with lung squamous cell carcinoma." (PMID 27760592, 2016). "The aim of this study was to observe the efficacy and safety of nimotuzumab, a anti-EGFR monoclonal antibody, combined with chemotherapy as second-or later-line in the treatment of advanced lung squamous cell carcinoma." (PMID 27760595, 2016). "Nimotuzumab combined with chemotherapy as second-or later-line therapy for advanced squamous cell lung carcinoma was active and well-tolerated, especially for those patients with EGFR positive." (PMID 27760595, 2016). "The relationship between molecular targeted therapy and status of EGFR or ALK genes in patients with lung squamous cell carcinoma needs further investigation." (PMID 27760592, 2016). "This reflects the fact that this is a retrospective study, thus patients were selected by clinicians who were probably more reluctant to prescribe EGFR-TKI in squamous cell lung cancer than in adenocarcinoma." (PMID 24408092, 2014). "The similar adverse prognostic role of cytoplasmic EGFR has been shown in squamous cell carcinoma of the lung." (PMID 19747398, 2009). "A similar adverse prognostic role of cytoplasmic EGFR staining demonstrated in our study has also been shown in squamous cell carcinoma of the lung." (PMID 14520458, 2003). "Eleven patients with squamous cell carcinoma of the head and neck and nine patients with squamous cell carcinoma of the lung, whose tumours expressed EGFR, were recruited." (PMID 8546911, 1996). "Additionally, Gefitinib and Cisplatin, combined with necitumumab and Gemcitabine, have demonstrated synergistic effects in lung squamous cell carcinoma by targeting EGFR signaling and DNA synthesis." (PMID 41405961, 2025). "Current data supporting that radiogenomic approach can identify epidermal growth factor receptor (EGFR) expression or be utilized to help to differentiate between adenocarcinoma and squamous cell carcinoma of the lung predicting diagnosis, prognosis, and optimal therapy." (PMID 39329997, 2024). "Unlike lung adenocarcinoma (LUAD), patients with lung squamous cell carcinoma (LUSC) have not benefited from targeted therapies such as EGFR tyrosine-kinase inhibitors (TKIs) due to the low mutation rate." (PMID 39443476, 2024). "Low DUSP3 expression is also observed in lung squamous cell carcinoma, which does not have EGFR mutation." (PMID 35705979, 2022). "The frequency of epidermal growth factor receptor (EGFR) mutations and the efficacy of tyrosine kinase inhibitor (TKI) in Chinese female patients with lung squamous cell carcinoma (SCC) are unknown." (PMID 33869057, 2021). "The Thai non-squamous cell carcinoma of the lung has up to 57% predominated EGFR mutation, contrary to the Western non-squamous lung cancer population, which has less than 10% prevalence of EGFR mutation." (PMID 33996532, 2021). "Further investigation of the crosstalk between the EGFR and PD-L1 pathways may be a rational approach to improve lung squamous cell carcinoma treatment." (PMID 34781919, 2021).
lung squamous cell carcinoma (continued). "Third, although we have performed comprehensive genomic characterization of EGFR-mutant squamous cell lung cancer and try to figure out why EGFR-mutant SCC confers poor responsiveness to TKI in terms of mutation profiles, the underlying mechanisms have not been verified in vitro and in vivo." (PMID 34195081, 2021). "The latest National Comprehensive Cancer Network recommends that EGFR mutations and other gene mutations should be considered as markers for lung squamous cell carcinoma, especially for non-smokers, small biopsy, or mixed squamous cell carcinoma." (PMID 31106047, 2019). "Among EGFR-mutated, squamous cell lung cancer patients, no comparative study has been conducted using EGFR-TKI." (PMID 31049758, 2019). "As we know, EGFR-mutated adenocarcinoma patients are likely to be young, women, nonsmokers, and Asian, while squamous cell carcinoma of the lung is believed to have a lower EGFR mutation rate, ranging from 0% to 15%21." (PMID 26923333, 2016). "Moreover, EGFR TKIs have also shown a modest therapeutic effect in lung squamous cell carcinoma (SCC), where EGFR mutations are very rare and patients have limited therapeutic options in the maintenance and relapsed settings." (PMID 26247735, 2015). "Membranous CD44v6 levels in tumors and surrounding samples obtained from 94 patients with squamous cell lung carcinomas were studied and compared to clinical stage, cellular proliferation, membranous CD44v5 levels, epidermal growth factor receptor EGFR and cytoplasmatic concentrations of CYFRA 21.1." (PMID 25809603, 2015). "However, in squamous cell lung cancer, the incidence of epidermal growth factor receptor (EGFR) gene mutant and ALK fusion gene are low, and targeted therapy like Tarceva and crizotinib, can hardly work." (PMID 24229629, 2013). "Although EGFR L858R mutation was detected throughout the transformation, genomic analyses were performed during the disease course, revealing the amplification of FGFR1 and NSD3, which have recently been proposed as potential driver oncogenes in lung squamous cell carcinoma." (PMID 40792216, 2025). "Therefore, to evaluate the potential versatility of EGFR-FabID in adherent cells and the commonality of proximity proteins of EGFR, the human lung squamous cell carcinoma cell line NCI-H226 was also used for EGFR exPPI analysis as a new adherent cancer cell line." (PMID 38097606, 2023). "However, the incidence of driver mutations in squamous cell lung cancers is extremely low, therefore EGFR/ALK/ROS1 mutations should have no impact on the findings reported for the stratified analysis on squamous cell lung cancer." (PMID 35045806, 2022). "Sapitinib (EGFR/HER2 inhibitor) was specific for HNSC and cervical squamous cell carcinoma and endocervical adenocarcinoma (CESC), esophageal carcinoma (ESCA), and lung squamous cell carcinoma (LUSC)." (PMID 33858332, 2021). "In lung squamous cell carcinoma, a positive yet weak correlation was observed between EZH2 expression and EGFR expression (r = 0.1122 and p < 0.001)." (PMID 33299862, 2020). "In lung squamous cell carcinoma, EZH2 expression is positively correlated with EGFR expression, but the correlation is weak (r = 0.1122 and p < 0.001)." (PMID 33299862, 2020). "The Combination of PKCι-PAK1 inhibitors was highly synergistic in EGFR and KRAS mutant adenocarcinoma and squamous cell carcinoma of the lung, in both in vitro and in vivo mice models." (PMID 31660987, 2019). "In contrast, none of the patients with squamous cell lung cancers, large cell cancers, or small cell neuroendocrine tumors exhibited EGFR positivity, aligning with findings from international studies." (PMID 39429333, 2024).